PRL (prolactin)
Diseases named in the same sentence as PRL in open-access papers (continued):
Sharing a sentence is not in itself a finding about the gene and the disease.
depression (continued). "We discuss the effects of PRL on neurogenesis and neuroprotection, the putative neuronal mechanisms underlying these effects, and their contribution to the onset of psychopathological states such as depression." (PMID 27065946, 2016). "Additionally, the greater predisposition to DEAs and the elevated cortisol and prolactin levels observed in the dysmenorrheic group may indicate heightened susceptibility to stress and depression in these young athletes." (PMID 40218947, 2025). "Informed by the in vitro results, we then tested whether overexpression of MG‐derived VDBP in the PrL region led to depression‐like behaviors in mice and further aggravates susceptibility of mice to CUMS, but if the conditional knockout of VDBP gene in mouse MG resulted in resilience." (PMID 39716879, 2025). "Chronic stress or depression can contribute to dysregulation of the hypothalamic–pituitary–adrenal axis, resulting in excessive cortisol secretion and suppressed prolactin expression." (PMID 40565372, 2025). "Previous studies indicate that plasma prolactin is significantly higher in females than males and is elevated in individuals with major depressive disorder." (PMID 40218947, 2025). "The main finding of this study is that overexpression of VDBP in the PrL region leads to depression‐like behavior and aggravates the CUMS‐induced phenotype via synaptic damage in mice, while conditional knockout of VDBP in MG plays a role against depression." (PMID 39716879, 2025). "To assess the impact of astrocyte-derived lactate on dendritic complexity within depression- associated mPFC subregions (ACC, PrL, and infralimbic cortex (IL)), we analyzed acute brain slices from Thy1-GFP transgenic mice subjected to CSDS." (PMID 41360776, 2025). "The reduced expression of Cx43 in the PrL region is a significant pathological feature of depression." (PMID 41360776, 2025). "This study also preliminarily suggested that an imbalance between E/I neurons due to biased activation of inhibitory neurons in the PrL region is a critical contributor to MG‐derived VDBP's role in depression." (PMID 39716879, 2025). "The PrL is involved in depression-like despair behaviour and maintaining attention to category-relevant information, and flexibly updates category representations, while the FrA is engaged in stimulus integration during associative learning." (PMID 39875098, 2025). "Prolactin results are equally interesting because recent studies have shown that females with major depression exhibit high levels of serum prolactin." (PMID 40292567, 2025). "The selective inhibition of IDO reversed ICV-STZ-induced depression-like behaviors by ameliorating neuroprotective branch deficits in the PrL and inhibiting neurotoxicogenic branch overactivation in the IL." (PMID 39000602, 2024). "This study attempted to unravel the knowledge gap between sex steroid hormones, epilepsy, and depression in WWE and found that changes in PRL and testosterone level are a potential biomarker of depression among PWE." (PMID 38711940, 2024). "The results of the study also support the view that reproductive system dysfunction resulting from E2 and PRL depletion can lead to depression." (PMID 39575307, 2024). "There was higher mean depression score, lower prolactin and higher testosterone level among cases compared to control." (PMID 38711940, 2024). "This study showed that astrocytes in the PrL and microglia in the IL were involved in regulating depression-like behaviors in the ICV-STZ model." (PMID 39000602, 2024). "Our results illustrate that mice with OVX lead to depression behavioral change in addition to acute fluctuation in E2 and PRL levels, together with the occurrence of alterations in the diversity and abundance of the gut flora occur." (PMID 39575307, 2024). "Although association between sex steroid hormones and depression exists, only PRL and testosterone predicted depression." (PMID 38711940, 2024).
depression (continued). "Clearly, changes in PRL and testosterone level are a significant biomarker of depression among PWE as the use of CBZ decreases the PRL level, which decreases the prevalence of depression." (PMID 38711940, 2024). "Altogether, all these data indicate PRL and their receptors as new candidates to be further explored in the migraine–depression comorbidity." (PMID 38397400, 2024). "We recently identified PRL as a gene contributing to PCOS risk and reported DRD2 conferring risk for type 2 diabetes and depression, which can both coexist with PCOS." (PMID 37563671, 2023). "In comparing abused children with depression, unabused children with depression, and unabused normal controls, it was found that the abused and depressed group had increased prolactin release after L-5-HTP stimulation compared to the other two groups." (PMID 37700748, 2023). "This study had several limitations; including missing data on a history of alcohol, consumption, the use of medicines like propranolol and spironolactone, prolactin levels, long-term cirrhosis symptoms, and the probability of depression in the patient." (PMID 36730272, 2023). "In adult studies, the most commonly used drug was fenfluramine, which showed a weakened prolactin response in patients with depression compared to controls." (PMID 37700748, 2023). "It is conceivable that increased stress stimulated elevated luteal PRL among women in the depression group and, consequently, increased premenstrual P4 levels which then set the stage for the development of depression symptoms." (PMID 37895130, 2023). "The results suggest that comorbidity of neuropathic pain/depression-induced by SNI significantly increased the Acp5 level in the PrL neurons." (PMID 35690777, 2022). "Changes in prolactin levels in affective disorders suggested the possibility of the prolactin as biochemical and neuroendocrinological biomarker in depression diagnosis." (PMID 36132219, 2022). "Taken together, the present study showed for the first time that the adaptation of PrL was modulated in the SNI-induced neuropathic pain/depression comorbid symptoms in rats." (PMID 35690777, 2022). "The predictor of severe depressive symptoms in postpartum women was higher thyroxine levels, while the predictor of depression appearing 6–10 weeks postpartum was higher progesterone and lower prolactin levels." (PMID 36430406, 2022). "Women who had previous episodes of depression had decreased prolactin and increased thyroid-stimulating hormone levels than those who had experienced depressive symptoms before." (PMID 36430406, 2022). "Taken together, the IL6/STAT3/Acp5 pathway modulated the excitability of PrL pyramidal neurons to change the adaption of PrL region, which critically involved in the development of comorbidity of neuropathic pain/depression." (PMID 35690777, 2022). "TNF, dopamine, calcium signaling pathway, prolactin, and I-kappaB kinase/NF-kappaB signaling play important roles in the pathogenesis of depression." (PMID 34479552, 2021). "Other indicators of decreased serotonin function in suicidal depression include prolactin insensitivity to fluoroamphetamine and abnormal platelet serotonin function." (PMID 32398015, 2020). "Yet, two previous studies found that mothers of term infants with high depression scores showed lower levels of prolactin four to six weeks after birth." (PMID 32296356, 2020). "Genetic associations were determined by sequentially regressing prolactin, BDNF, 17-items Hamilton's Depression (HAMD-17) and Clinical Global Impression scale, Severity (CGI-S) ratings, and depression (absent/present) on the available SNPs." (PMID 32116853, 2020). "Here, we will summarize some aspects of PRL actions within the brain and their contribution to the onset of psychopathological states like depression." (PMID 27065946, 2016).
depression (continued). "Depression and antidepressant therapy that interferes with the prolactin metabolism, promotes the progression of endometriosis and adenomyosis, acting as a mitogen at the myometrial and endometrial level." (PMID 27453751, 2016). "Change in Hamilton Depression Scale, prolactin levels, sex, and reported adverse events of extrapyramidal symptoms, sedation, and movement disorders were not significant predictors of satisfaction." (PMID 17054789, 2006). "Moreover, elevated PRL levels in postpartum depression patients were found to be positively correlated with scores on the Edinburgh Postnatal Depression Scale." (PMID 40565372, 2025). "Finally, depression was negatively associated with FT4 (Spearman’s rho=-0.229, p=0.030), and positively with PRL (Spearman’s rho=0.237, p=0.018) levels." (PMID 41210497, 2025). "Additionally, microinjection of the selective IDO inhibitor 1-Methyl-DL-tryptophan (1-MT) in the PrL or IL alleviated depression-like behaviors by reversing these different abnormalities in the PrL and IL." (PMID 39000602, 2024). "Changes in PRL levels have not been associated with mood disorders, but it is known to interact with estrogen pathways to influence depression due to its effects on dopaminergic pathways and hypothalamic–pituitary–ovarian axis (HPO) modulation." (PMID 39575307, 2024). "In addition to presenting the effects of hypoprolactinemia on depression and sexual functions, the present study has demonstrated cut-off levels for basal and stimulated PRL levels for the diagnosis of hypoprolactinemia in different genders." (PMID 38700812, 2024). "The results indicated that among the top 20 pathways of PPT for depression, chemical carcinogenesis-receptor activation pathways in cancer, the prolactin signaling pathway, the PI3K-AKT signaling pathway, and endocrine resistance should be the focus of further research." (PMID 39062817, 2024). "However, only LP PRL [B 0.038, std error 0.018, 95% CI 0.001–0.075; p0.042] and testosterone [B −0.806, std error 0.116, 95% CI −1.037 to −0.574; p0.000] predicted depression." (PMID 38711940, 2024). "The endocrine data in this study suggest that any deviation from the secretory pattern of T and PRL characteristic of those in the non-depression group may be related to depression symptoms observed in women in the susceptible group." (PMID 37895130, 2023). "To date, the focus has been on blocking P-glycoprotein to increase the penetration of many drugs in the brain; nevertheless, the manipulation of PRL levels may be equally important in the treatment of drug-resistant depression." (PMID 36833950, 2023). "If the deficits of the dopaminergic system are substantial, PRL concentrations from the pituitary gland of women in the depression group may increase significantly and contribute to increased T secretion." (PMID 37895130, 2023). "Mothers with worse depression symptoms tend to present with lower prolactin and higher cortisol concentrations, which may affect the lactation reflex, leading to DOLII." (PMID 36451171, 2022). "In addition, an increasing number of research have demonstrated that lactation is closely connected with depression, inducing a less maternal behavior in dams, which is related to a decrease of oxytocin (OT) and prolactin (PRL) levels." (PMID 34441640, 2021). "PRL also enhances serotonin synthesis which increases PRL activating factors and reduces dopamine, thus more hyperprolactinemia occurs leading to anxiety and depression." (PMID 33995058, 2021). "Altogether, these results indicate that the predisposition to depression in LR rats may be attributed to the low PNN density and neurocan expression in the PrL." (PMID 32116542, 2020). "Moreover, several other neuropeptides of substance P, opioids, oxytocin, and prolactin are released during stress and depression, which induces gastric mucosal hypoperfusion and gastric hypomotility." (PMID 32020020, 2020).
depression (continued). "As far as we know, a possible association between PRL polymorphisms and depressive disorder had not yet been studied." (PMID 32116853, 2020). "Moreover, alterations in neuroendocrine responses to L-5HTP challenge tests, such as the prolactin hypersecretion and hyposecretion of cortisol found in healthy children, have been suggested to represent a trait marker for depression in children." (PMID 15774013, 2005). "However, only prolactin (p0.042) and testosterone (p0.000) predicts depression among WWE." (PMID 38711940, 2024). "In addition, the endogenous level of PRL may serve as a predictor of a patient’s response to pharmacotherapy, which was shown in the case of depression." (PMID 36833950, 2023). "However, whether and how the adaptation of PrL contributes to the comorbidity of neuropathic pain and depression are unknown." (PMID 35690777, 2022). "However, whether or how the inflammation cytokine in PrL be involved in the nerve injury-induced neuropathic pain and depression-like symptoms in rats are currently unclear." (PMID 35690777, 2022). "In this study, we also noted that oxytocin as well as prolactin levels decreased after 8 weeks of chronic stress both in female mice and more in male mice, which suggests that oxytocin monitor might also be meaningful for male patients with depression." (PMID 36132219, 2022). "However, whether PrL participated in the neuropathic pain/depression comorbid behavior in rats is largely unclear." (PMID 35690777, 2022). "However, whether long term harmful stimulation such as spared nerve injury (SNI) can change intrinsic activity of PrL and contributed to the comorbidity of neuropathic pain and depression are largely unknown." (PMID 35690777, 2022). "Furthermore, and despite the gender by age interaction on prolactin, we did not observe a similar gender or age modification of the genetic association with either depression status or prolactin/BDNF." (PMID 32116853, 2020). "The association between age and prolactin was modified by gender, but not by depression status." (PMID 32116853, 2020). "Moreover, in the CSDS model, the expression of Cx43 and its co-localization with IDH3α in the PrL were significantly diminished, suggesting that the reduced interaction between Cx43 and IDH3α might contribute to the pathogenesis of depression." (PMID 41360776, 2025). "ICV-STZ significantly increased the Kyn/Trp ratio in the PrL and IL, which indicated that IDO activity was elevated in these two brain regions when these rats exhibited depression-like behaviors." (PMID 39000602, 2024). "We found that intra-PrL or intra-IL injections of 1-MT decreased IDO activation and improved multiple depression-like behaviors in ICV-STZ rats." (PMID 39000602, 2024). "Reduced levels of β-Arrestin1 protein in women with Hamilton Rating Scale for Depression (HAM-D) scores above 19 were observed alongside significantly higher plasma testosterone and prolactin concentrations." (PMID 37895130, 2023). "However, it is not known whether the altered T and PRL secretion reflects a cause or effect of depression." (PMID 37895130, 2023). "To further confirm the role of Acp5 in pyramidal neurons of PrL in the comorbidity of neuropathic pain and depression in rats, we overexpressed the Acp5 by bilateral injection of AAV–DIO–Acp5–EGFP into the PrL together with AAV–CaMKIIa–Cre." (PMID 35690777, 2022). "In the present study, we established a rat comorbidity model of neuropathic pain and depression-like behavior on weeks 5 following SNI, and observed the intrinsic spontaneous activity of PrL by examining the change of ALFF in this model." (PMID 35690777, 2022). "According to the results of this study, we can carry out research on prolactin signaling pathway and EGF in the future depression research." (PMID 34479552, 2021). "This research indicated that prolactin signaling pathway and EGF play an important role in the treatment of depression." (PMID 34479552, 2021).
depression (continued). "A total of 56 signaling pathways (P < 0.05) were identified by Kyoto Encyclopedia of Genes and Genomes analysis, mainly involving depression-related pathways such as dopaminergic synapse, TNF signaling pathway, and prolactin signaling pathway." (PMID 34479552, 2021). "Protein-protein interaction and KEGG enrichment analysis results show that prolactin signaling pathway and EGF play an important role in the treatment of depression." (PMID 34479552, 2021). "The aim of the present study was to investigate the possible relationship between being depressed and BDNF and PRL genotypes, on one hand, serum BDNF and PRL levels on the other, with special reference to severity of depression." (PMID 32116853, 2020). "(c) Do the Cg1, PrL, IL, and BLA contribute to fluoxetine treatments in PTSD's fear and depression symptoms?" (PMID 33299494, 2020). "Research in the field of hormones like testosterone, prolactin and IGF-1 as individual biomarkers and putative predictors of clinical outcomes (e.g., hypertension, depression, inflammation) has been especially successful." (PMID 24886498, 2014). "Our male patient had normal hormone status (prolactin, beta-hCG, testosterone, E2, LH, FSH, T3, T4), and denied taking any drugs except for those he was taking for hypertension and depression." (PMID 23531415, 2013). "Specifically, the neuroprotective branch is diminished in the PrL, and the neurotoxicogenic branch is enhanced in the IL, which may be involved in the development of ICV-STZ-induced depression-like behaviors." (PMID 39000602, 2024). "However, the use of CBZ is limited due to the effects of drug–drug interaction involving the cytochrome p450; hence, the use of CBZ decreases the PRL level, in turn decreasing the prevalence of depression, while the use of LEV increases the PRL level." (PMID 38711940, 2024). "Therefore, this study investigated depression-like behavior and the neurophysiological mechanism of action of IDO on Kyn pathways in the PrL and IL in the rat model of ICV-STZ." (PMID 39000602, 2024). "Interpretation of the significance of the altered changes in T and PRL in the depression group is surrounded by the lack of knowledge of the precise stage at which depression symptoms are triggered during the luteal phase of the menstrual cycle." (PMID 37895130, 2023). "Serum PRL concentrations (ng/mL) were approximately 103% higher (p < 0.0001) in the depression group compared to those in the non-depression group." (PMID 37895130, 2023). "In the present study, we found that rats showed the comorbidity of mechanical allodynia and depression-like behavior on weeks 5 following SNI, and the results of fMRI and electrophysiology indicated that the activity of PrL pyramidal neurons were significantly decreased in the comorbid rats." (PMID 35690777, 2022). "In particular, hormonally induced changes in the brain levels of norepinephrine, oxytocin, prolactin, and GABA during pregnancy and lactation may induce depression." (PMID 33692667, 2021). "The associations of prolactin and BDNF levels with the presence of depression was non-significant: OR 1.19 (95%CI 0.85; 1.68) for ln(prolactin), and OR 1.03 (95%CI 0.58; 1.84) for ln(BDNF)." (PMID 32116853, 2020). "We compared women aged below (N = 65) and above 40 (N = 109) for (a) mental health status with the Positive and Negative Syndrome Scale (PANSS) and Montgomery Asberg Depression Rating Scale; (b) current medications and (c) prolactin levels, at baseline and at follow-up (12/15 months later)." (PMID 41327590, 2025). "Next, to evaluate directly whether the activation of IDO in the PrL and IL is responsible for depression-like behavior in ICV-STZ rats, we subsequently inhibited IDO by microinjecting 1-MT in the PrL or IL and observed its effects on the behaviors of ICV-STZ rats." (PMID 39000602, 2024).